RNU4-32P (RNA, U4 small nuclear 32, pseudogene)
Gene: Small nuclear RNA gene on chromosome 12 (109,567,975 to 109,568,115, reverse strand). Ensembl gene ENSG00000200274.
Homologues: Orthologues: chimpanzee U4 (99% identical). Paralogues in human: RNU4-10P (80% identical), RNU4-49P (79% identical), RNU4-79P (78% identical), RNU4-81P (76% identical), RNU4-83P (74% identical), RNU4-17P (74% identical), RNU4-28P (73% identical), RNU4-50P (73% identical), RNU4-51P (71% identical), RNU4-90P (70% identical), RNU4-46P (70% identical), RNU4-15P (68% identical), and 82 more.